SIRT1 (sirtuin 1)
Diseases named in the same sentence as SIRT1 in open-access papers (continued):
Sharing a sentence is not in itself a finding about the gene and the disease.
cancer (continued). "In addition to the SIRT1-SREBP signaling pathway, microRNAs can also downregulate SREBPs in cancer cells through the following signaling pathways." (PMID 36969840, 2023). "GAS5 can inhibit malignant progression of colorecatl cancer cells through regulating macroautophagy and forming a negative feedback loop with the miR-34a/mTOR/SIRT1 axis (Zhang HG." (PMID 37441551, 2023). "SIRT1, a highly conserved nicotinamide adenosine dinucleotide (NAD+) dependent class III histone deacetylase, is able to interact with and deacetylate c-Myc in cancer cells, which in turn increase its stability and activity." (PMID 37554307, 2023). "In addition, the SIRT1/FOXO signaling pathway protects cells through autophagy, thereby reducing skin cellular senescence, inflammation, and cancer." (PMID 36835162, 2023). "In cancer cells, the BRD4 inhibitor JQ1 induces ferroptosis by enhancing the expression of an HDAC named SIRT1, which decreases the H3K27ac level at upstream of BRD4, ultimately affecting the recognition of acetylation sites on the histones at GPX4 and SLC7A11 genes." (PMID 37229485, 2023). "SIRT1, a NAD-dependent class III histone deacetylase, has a dual role in cancer." (PMID 37949849, 2023). "For the same reason, the use of NNMT inhibitors, widely studied for anti-cancer applications, should be carefully evaluated in order to prevent negative effects consequent to SIRT1 inhibition." (PMID 36829935, 2023). "Given the variety of molecular consequences evoked by these inhibitors, inhibition of SIRT1 and oncogenic HSP90 circuit will likely collapse cellular epichaperomes and disturb the broad spectrum of their subordinate processes, decreasing cancer cell metabolic fitness, proliferation and viability." (PMID 37816710, 2023). "Some mitomiRs specifically regulate mitochondrial metabolism (mir-149 controls PARP2 and SIRT1 expression, mir-326 regulates PKM2 expression in cancer cells, mir-25 controls Ca uptake and ROS production, and mir-128a regulates BMI-1 expression to ensure redox homeostasis)." (PMID 36496979, 2022). "Additionally, SIRT1 plays a pivotal role in the regulation of the epithelial-mesenchymal transition (EMT) process, which contributes to the metastasis of cancer cells." (PMID 35927590, 2022). "Sirtuin 1 (SIRT1), a nicotinamide adenine dinucleotide (NAD+)-dependent histone deacetylase (HDAC), has been shown to regulate multiple biological processes including aging, inflammation, autophagy, cancer, and metabolic diseases." (PMID 35959106, 2022). "One study showed synergic activity when inhibiting SIRT1 expression with tenovin-6 combined with metformin, with a significant reduction in cell proliferation for the overexpressed SIRT1 cancer cells, regardless of LKB1 function." (PMID 35890085, 2022). "It was also proposed that sirtuins, especially SIRT1 and SIRT2, might play essential roles in the maintenance and differentiation of various cancer stem cells." (PMID 35326523, 2022). "Therefore, this study aimed to explore the anti-cancer property of elaiophylin in LADC using in vitro and in vivo models as well as the involvement of SIRT1-related signaling in such an effect of elaiophylin." (PMID 36497294, 2022). "Notably, miR-199b downregulation has been described to be associated with increased cell invasion and migration in CRC, promoting cancer progression and metastasis by SIRT1/CREB/KISS1 signaling pathway regulation, SIRT1 being a direct target of this miR." (PMID 35216319, 2022). "Interestingly, SIRT1 gene silencing upregulated the expression of the EMT-related protein E-cadherin and cancer stemness markers kruppel-like factor 4 (KLF4) and aldehyde dehydrogenase 1 family member A1 (ALDH1A1)." (PMID 36291902, 2022).
cancer (continued). "Sirt1 is the first identified nicotinamide-adenine dinucleotide (NAD+)-dependent HDAC, and it regulates various biological processes such as cellular senescence, AD, cancer and neuroinflammation." (PMID 35668361, 2022). "In cancer, DYRK3 was proposed to act in parallel with DYRK1A to promote cell survival under stressful conditions by phosphorylating nicotinamide adenosine dinucleotide (NAD)-dependent deacetylase SIRT1." (PMID 35454940, 2022). "Many previous studies have reported the cancer‐promoting potential of USP22, including the induction of cell proliferation and DNA repair, activation of c‐Myc/NAMPT/SIRT1‐dependent FOXO1 and YAP signaling, and deubiquitination of CD274 to suppress anticancer immunity." (PMID 34743406, 2022). "Previous reports have suggested that overexpression of sirtuins in vivo may have detrimental effects, for example SIRT1 and SIRT7 overexpression is reported to be an indicator of poor prognosis in some cancers." (PMID 36561039, 2022). "In this study, WGCNA uncovered a negative correlation between SIRT1 and cancer cells based on scRNA-seq transcriptome, indicating its suppression on GC development." (PMID 36324577, 2022). "Furthermore, it is reported that SIRT1 can regulate cell migration and invasion in several cancer cells by deacetylating various substrates, and the vascular remodeling of the placenta also depends on the invasive properties of trophoblasts, so we consider whether SIRT1 also affects pre-eclampsia." (PMID 35327614, 2022). "Zhang’s team demonstrated the increased expression of SIRT1 in all examined cancer stages compared to mucosa without neoplasm." (PMID 36499440, 2022). "Previous studies showed that Sirt1 might regulate autophagy due to deacetylation of Atg5, Atg7, or LC3 in cancer cells, MEFs, germ cells, and stem cells." (PMID 33723227, 2021). "This study reported for the first time that CK2 down-regulation in human cancer cells enhances the expression of SASP factors (IL-1β, IL-6, and MMP3) by NF-κB activation through two pathways: an SIRT1-dependent/AKT-independent pathway and an SIRT1/AKT-dependent pathway." (PMID 33401686, 2021). "Recent reports show that the expression of SIRT1 protein is significantly overexpressed in non-tumor liver tissues adjacent to cancer, and the elevated SIRT1 level is related to tumor grade and predicts poor prognosis." (PMID 33955831, 2021). "This is the first study to demonstrate that the circ-SIRT1/EIF4A3/N-cadherin/vimentin axis promotes the proliferation and EMT of CRC cells, providing a novel therapeutic target and strategy for the treatment of this cancer." (PMID 34660182, 2021). "Moreover, SIRT1 is involved in regulating the expression of STAT3 in various diseases, including cancer, diabetic kidneys and hepatic gluconeogenesis." (PMID 34044769, 2021). "Signal pathways such as AMP-activated protein kinase (AMPK), mammalian target of rapamycin (mTOR), and sirtuin 1 (SIRT1) and autophagy-related pathways may also bridge T2D and CRC and participate in cancer progression." (PMID 34434893, 2021). "Unlike 4-BR modulating SIRT3, resveratrol stimulates SIRT1 activity and expression to inhibit cancer stemness." (PMID 35723384, 2021). "Although Sirt1 upregulates ROS expression, leading to cancer cell death, Sirt1 itself does not promote cell death to the same extent." (PMID 33727672, 2021). "Therefore, our present study discovered new roles of SIRT1 in genome stability by modulating extrachromosomal gene amplification and RIGS, potentially leading to important implications in cancer malignancy and protein expression." (PMID 33539925, 2021). "However, in cancer cells, AMPK activated by metformin can further activate the SIRT1/NF- κB pathway, induce mitochondrial dysfunction, and trigger cancer cell pyroptosis." (PMID 34616289, 2021).
cancer (continued). "A direct comparison of NH4-6, which inhibits SIRT1-3, and NH4-13, which only inhibits SIRT2, showed that selective SIRT2 inhibition could be advantageous when treating cancer." (PMID 34650436, 2021). "SIRT1 has been found to rescue cells from oxidative-stress-induced apoptosis by promoting ubiquitination and degradation of FOXO but in cancer cells these pathways could be dysregulated, resulting in activated apoptosis." (PMID 35052372, 2021). "Notably, NAM primarily seems to exhibit its chemotherapeutic capacity by suppressing SIRT1 and PARP1, as already shown in preclinical models of diverse cancers." (PMID 32245130, 2020). "Although the role of SIRT‐1 in the regulation of cell cycle, metastasis, and differentiation of tumor cells has been studied in some cancers, its role in other types of cancer has not been well evaluated." (PMID 33133558, 2020). "However, knowledge is still limited regarding the interplay between SIRT1 and GPER modulation in cancer progression." (PMID 33330467, 2020). "SIRT1 and SIRT4 significantly decreased in 7 cancer types and 9 cancer types, respectively." (PMID 32158696, 2020). "Besides playing critical roles in the initiation, promotion, progression, and metastasis of cancer, AHR is involved in the regulation of two NADases, contributing to decreased SIRT1 activity and the deregulation of glucose and fatty acid homeostasis as well." (PMID 32117717, 2020). "SIRT1, a NAD-dependent class III histone deacetylase (HDAC), is involved in various physiological and pathophysiological processes, including neurodevelopment, aging, metabolism, inflammation, and cancer." (PMID 32148659, 2020). "In cancer cells, the capsaicin-triggered inhibition of tNOX was previously shown to decrease the intracellular NAD+/NADH ratio and suppress NAD+-dependent sirtuin 1 (SIRT1) deacetylase activity." (PMID 31635402, 2019). "While being strongly suppressive in cancer, melatonin mainly stimulated SIRT1 in nontransformed cells, especially in the context of aging." (PMID 30862067, 2019). "Our findings also suggest that SIRT1 and SIRT6 also play a coordinate role in fine-tuning FOXO3 acetylation and therefore lapatinib sensitivity by setting a threshold for the de-acetylation activity in both lapatinib sensitive and resistant cancer cells." (PMID 31357743, 2019). "Previous studies focusing on SIRT1, do not support a critical role for this sirtuin family member in CR-mediated cancer prevention." (PMID 31970087, 2019). "Collectively, the current body of literature suggests that SIRT1 expression has a pro-tumorigenic role in HCC but is not a cancer-initiating event." (PMID 31608282, 2019). "SIRT1-induced PGC-1α increased mitochondrial copy numbers and mass, cellular ATP levels, DNA transcript levels, and mitochondrial biogenesis, which boosted the migration and invasion of HCC, thus promoting cancer dissemination." (PMID 31608282, 2019). "Hence, the overexpression of SIRT1 in BC cells has the potential to facilitate aberrant regulation through these system, thus contributing for the EMT process and cancer progression." (PMID 30319540, 2018).
cancer (continued). "Sirtuin-1 (SIRT1), the mammalian ortholog of yeast Sir2p, is well known to be a highly conserved NAD+-dependent protein deacetylase that has been emerging as a key cancer target." (PMID 29991742, 2018). "Deacetylation of cortactin by SIRT1 and HDAC6 promotes cancer cell migration and invasion, which also could be observed in p300-null cells." (PMID 29416718, 2018). "Unlike other sirtuin family members, SIRT1 can shuttle between the nucleus and cytoplasm and was reported to be a tumor suppressor or tumor promoter in various cancers." (PMID 30513573, 2018). "Altogether these results indicate that the inhibition of SIRT1 and SIRT2 activities by eurochevalierine may account for its cytostatic anti-cancer properties observed previously." (PMID 29401749, 2018). "Strikingly, both proteins have been recognized for their dualistic contribution to cancer, suggesting that the context-specific dualism of PGC-1α might correlate with AMPK or SIRT1 statuses." (PMID 29629336, 2018). "Likewise, FCCP activates the Sirt1/AMPK signaling; however, the anti-migratory effect is non-cancer cell selective." (PMID 30181620, 2018). "Cancer cells show increased metabolism through aerobic glycolysis and higher NAD turnover in order to sustain fast proliferation, relative genomic stability, persistent DNA repair, and higher activity of the NAD-dependent deacetylase SIRT1." (PMID 28160567, 2017). "Together, these results show that SIRT1 is triggering MYC target gene expression by inhibiting MXD1 function, which may contribute to cancer phenotype acquisition." (PMID 29383100, 2017). "Elevated SIRT1 expression was found in hepatocarcinoma cells when compared to non-cancerous hepatocytes, and NAMPT inhibition led to cell death via the AMPK/mTOR pathway, offering a novel strategy to prevent cancer cell growth in vivo." (PMID 28160567, 2017). "Sirtuin 1 (Sirt1) is a multifaceted class III histone deacetylase involved in a wide variety of cell processes, ranging from cancer to ageing, which has been conserved throughout evolution from yeast to human and is a crucial link between cell metabolism, longevity and stress response." (PMID 29200988, 2017). "SIRT1 is overexpressed in CD34+ AML, with a minimal role in normal hematopoietic cells but involvement in metabolism, cell cycle control, metabolism, DNA repair and survival of cancer cells." (PMID 28978059, 2017). "SIRT1 is expressed in human HCC carcinoma tissues at a higher level than in adjacent nontumor liver tissues." (PMID 27935857, 2017). "Moreover, high SIRT1 expression was detected in 19/96 (19.8%) adjacent NNM tissues and 53/96 (55.2%) cancer tissues." (PMID 28070138, 2016). "To examine whether SIRT1-induced AR and MMP3 promote cancer proliferation, we co-cultured B16F10 with MEF-1 treated with siRNAs targeting them." (PMID 26992208, 2016). "In the present study, we hypothesized that Sirtuin 1 and 2 (SIRT1/2), class III histone deacetylases (HDACs), were critical in controlling the destiny of bulk tumor cells and cancer stem cells (CSCs) of UM." (PMID 26940009, 2016). "Sirtuin 1 (SIRT1) is an NAD-dependent deacetylase involved in telomeric maintenance, and may act as a tumor promoter or suppressor depending on the type of cancer in which it is implemented." (PMID 27242892, 2016). "Collectively, our data reveal that SIRT1 may be engaged by GPER signaling toward tumor progression and pro-survival effects elicited by estrogens in cancer cells and main components of the tumor microenvironment like CAFs." (PMID 26225773, 2015). "Sirtuin 1 (SIRT1), a nicotinamide adenosine dinucleotide (NAD+)-dependent deacetylase, is widely recognized as a critical regulator in metabolic disease, aging, and cancer development." (PMID 25905708, 2015).
cancer (continued). "Thus, ACSS2/CBP/SIRT1/HIF-2 signaling links nutrient sensing and stress signaling with cancer growth and progression in mammals." (PMID 25689462, 2015). "Moreover, this is the first study exploring the prognostic value of the simultaneous expression of SIRT1 and SIRT2 in the same cancer patient." (PMID 25915617, 2015). "Secondly, high glucose increased Nampt and Sirt1, which may provide a possible mechanism for MDR in patients and a lower inhibition rate with anticancer drugs in the cancer cell line." (PMID 25815791, 2015). "Therefore, it is plausible that down-regulation of SIRT1 would prevent 17-AAG-mediated induction of HSF1, Hsp70 and P-gp, and consequently sensitize cancer cells to 17-AAG." (PMID 26416354, 2015). "We chose ERK, TGFB1, TGFB2, SIRT1, IL-6, PI3K, and WHSC1 (which were controlled by several genes) and three other genes AR, BCL-XL, and CCND1 that could mark the deterioration of the cancer, for testing." (PMID 26603105, 2015). "HDAC expression is generally elevated in cancer for example HDAC1, 2, 3 and 6 are reported to be upregulated in various cancers but some HDACs, such as HDAC1, 2 and SIRT1, may also be lost or decreased." (PMID 26426052, 2015). "Moreover, we disclose that GPER and SIRT1 have an important role in the pro-survival effects prompted by E2 and the selective GPER ligand G-1 in cancer cells and CAFs treated with etoposide." (PMID 26225773, 2015). "Other studies have shown that nuclear SIRT1 expression was detected in about 28% of pancreatic ductal adenocarcinoma (PDAC), and expression was found to be significantly higher in poorly differentiated carcinomas." (PMID 25569080, 2015). "Another Sirt1 inhibitor (EX-527) is in clinical trial, albeit for Huntington's Disease and not (yet) for cancer." (PMID 25594010, 2014). "Additionally, we examined 21 pairs of oral normal and cancer tissues obtained from OSCC patients and tested them for SIRT1 mRNA expression." (PMID 25424420, 2014). "The results showed the expression level of SIRT1 protein was significantly lower in cancer than normal tissues (p = 0.000), then, the expression level of N1IC and Snail were markedly up-regulated in cancer tissues (p = 0.027, p = 0.001, respectively)." (PMID 25420528, 2014). "In the present study, NAM was used to examine the role of SIRT1 in the stress response and it was observed that NAM had a synergistic effect with low concentrations of antitumor agents, thus increasing chemosensitivity in the course of cancer chemotherapy." (PMID 24137378, 2013). "Salermide and Sirtinol inhibit Sirt1 and Sirt2 and they induce apoptosis in cancer cell lines, but not normal cell lines." (PMID 24069483, 2013). "Although several SIRT1 activating compounds have been recently developed, the anti-cancer effects of these compounds have not been reported." (PMID 23846322, 2013). "Augmented SIRT1 expression was observed only at low concentrations (>80% cell viability) and the inhibition of SIRT1 deacetylase by NAM decreased the viability of the cancer cells exposed to low concentrations of antitumor agents." (PMID 24137378, 2013). "It was found that the SIRT1 mRNA expression decreased significantly in carcinomas compared with adjacent noncancerous mucosae (P = 0.02, 1.28-fold)." (PMID 23805287, 2013).